HEY1 (hes related family bHLH transcription factor with YRPW motif 1)
Diseases named in the same sentence as HEY1 in open-access papers (continued):
Sharing a sentence is not in itself a finding about the gene and the disease.
hepatocellular carcinoma (8 papers, 2019 to 2025). A malignant tumor that arises from hepatocytes. "The HGF-mediated c-Met/FRA1/HEY1 cascade may be the key to inducing the transition from cirrhosis to hepatocellular carcinoma." (PMID 33718161, 2021). "We have also shown that targeting the c-Met/FRA1/HEY1 cascade mediated by HGF could be a promising treatment strategy for hepatocellular carcinoma (HCC) since the tumor-initiating cells of the liver are regulated by CAFs together with HGF secretions." (PMID 34202411, 2021). "Consequently, they suggest that targeting the c-Met/FRA1/Hey1 cascade mediated by CAF-derived HGF could serve as a potential therapeutic approach for hepatocellular carcinoma (HCC)." (PMID 38791916, 2024). "Under pathological conditions, HEY1 and CEBPD exhibit opposing roles in hepatocellular carcinoma: HEY1 promotes metastasis, while CEBPD functions as a tumor suppressor gene." (PMID 41421763, 2025). "Further, it has been shown that HEY1, a HIF-1 target, decreases mitochondrial biogenesis by repressing the expression of PTEN-induced kinase 1 (PINK1) in human hepatocellular carcinoma cells through a HIF-1–dependent mechanism." (PMID 36421698, 2022).
lung carcinoma (6 papers, 2012 to 2023). "Notably, SIRT1-deficient lung cancer-derived ECs overexpressing N1IC displayed a markedly enhanced level of HEY1 and HEY2 activity." (PMID 23028940, 2012). "Similarly, PNO1/CRISPR/Cas9 inhibited the expression of Notch target genes Hes1 and Hey1 in lung cancer A549 and H460 cells." (PMID 36625087, 2023). "Several studies reported the important role of Nocth2, Nocth4 and Hey1 in lung cancer progress." (PMID 32483111, 2020). "High HEY1 levels were prognostic of better overall survival in both types of lung cancer patient." (PMID 29743479, 2018). "In contrast, activation of SIRT1 signaling through the use of the small molecules SRT1720 or SRT2183 inhibited DLL4-mediated induction of HEY1 and HEY2 expression, indicating that SIRT1 negatively modulated DLL4/Notch1 signaling in lung cancer-derived ECs." (PMID 23028940, 2012). "Similarly, the silencing of SIRT1 significantly enhanced HEY1 and HEY2 expression in lung cancer-derived ECs in response to DLL4 stimulation, whereas no changes were observed in unstimulated lung cancer-derived ECs." (PMID 23028940, 2012).
lymphoma (6 papers, 2013 to 2023). A malignant (clonal) proliferation of B- lymphocytes or T- lymphocytes which involves the lymph nodes, bone marrow and/or extranodal sites. "HEY1 belongs to the inhibitory subgroup of bHLH proteins, deregulation of which promotes the development of leukemia/lymphoma affecting the function of E2A in driving lymphoid development." (PMID 23637834, 2013). "Similarly, in the context of lymphoma, a specific population of lymphoma cells was shown to up-regulate endothelial Jagged1, through the secretion of FGF4, which in turn up-regulates Notch2 and consequently Hey1 in the tumor cells promoting growth, aggressiveness and resistance to chemotherapy." (PMID 26213336, 2015).
mesenchymal chondrosarcoma (6 papers, 2014 to 2024). A morphologic variant of chondrosarcoma arising from bone and soft tissue. "Most cases of mesenchymal chondrosarcoma are associated with a recurrent fusion between HEY1 and NCOA2 resulting from intrachromosomal deletion of 8q." (PMID 37212282, 2023). "Newer findings also question well-accustomed “golden rules” including the detection of HEY1::NCOA2 fusions in tumors other than mesenchymal chondrosarcoma and reports on rare USP6-rearranged cases of malignant nodular fasciitis." (PMID 38231260, 2024). "Our findings show 2 variants of the HEY1-NCOA2 gene fusion: HEY1 (exon 4)-NCOA2 (exon 13) and HEY1 (exon 4)-NCOA2 (exon 14), in both mesenchymal chondrosarcoma patients." (PMID 30819134, 2019). "The pathogenetic mechanisms behind this nonrandom involvement are unknown, but the presence on 8q of two genes, HEY1 and NCOA2, now known to be involved in mesenchymal chondrosarcoma tumorigenesis is, of course, suggestive." (PMID 24839999, 2014).
chondrosarcoma (5 papers, 2015 to 2025). A malignant cartilaginous matrix-producing mesenchymal neoplasm arising from the bone and soft tissue. "This study demonstrated that human HEY1::NCOA2 expression in embryonic chondrogenic progenitors successfully developed mesenchymal chondrosarcoma." (PMID 37212282, 2023). "HEY1 fusions are often found as oncogenic mutations in chondrosarcoma, but their role in modulating gene dependency has not been specifically interrogated." (PMID 37242535, 2023). "Finally, shRNA-mediated gene silencing of HEY1::NCOA2 abrogated growth of mesenchymal chondrosarcoma cells in vitro, indicating that the survival and proliferation of mesenchymal chondrosarcoma are dependent on HEY1::NCOA2 expression." (PMID 37212282, 2023). "Rearrangements involving ESWR1 gene were detected in two fibrosarcomas and one sarcoma (not specified); two mesenchymal chondrosarcomas showed the characteristic HEY1::NCA2 fusion." (PMID 37708140, 2023). "Further characterization of Notch/HEY1 target gene expression and NCOA2-related nuclear receptor target genes in mesenchymal chondrosarcoma may provide insight into avenues for treatment with targeted therapies." (PMID 26146478, 2015).
colon cancer (5 papers, 2016 to 2024). "mRNA expression levels of NOTCH-1, NOTCH-3, NOTCH-4, JAG-1, DLL-4, Hes-1, and Hey-1 were quantified to elucidate the action of endostatin/CTX on the notch signaling pathway in colon cancer." (PMID 26762567, 2016). "Analysis of colon cancer cells individually overexpressing each of the four isoforms revealed an increased basal Notch signaling in NUMB2 and -4, as shown by the expression of the ‘universal’ targets HES1 and HEY1." (PMID 36346211, 2022).
pancreatic cancer (4 papers, 2012 to 2025). "HES1 expression was significantly upregulated in pancreatic cancer tissues and correlated with poor prognosis, while HEY1 was also identified as a prognostic biomarker." (PMID 41200204, 2025). "Overexpression of JAG1 also induced HES1, but not HEY1, in the pancreatic cancer cell line XPA3." (PMID 25557173, 2015).
rhabdomyosarcoma (4 papers, 2017 to 2025). A rare aggressive malignant mesenchymal neoplasm arising from skeletal muscle. "Despite these studies uncovering important roles for NOTCH1 in regulating rhabdomyosarcoma growth, roles for NOTCH1 or HEY1 in regulating stem cell programs that elevate overall numbers of TPCs was not reported." (PMID 28614716, 2017). "Highlighting Notch-mediated maintenance of an undifferentiated state in rhabdomyosarcoma, pathway inhibition using a γ-secretase inhibitor or direct inhibition of NOTCH3, HEY1 or HES1 increases the expression of myogenic differentiation factors and drives muscle-like differentiation." (PMID 40983796, 2025).
gastric cancer (3 papers, 2021 to 2024). A primary or metastatic malignant neoplasm involving the stomach. "Gastric cancer patients exhibiting high NOTCH2 or HEY1 expression had significantly poorer prognosis than those with lower levels, respectively." (PMID 39524442, 2024). "Overall, these findings suggested a potential mechanism that MFAP5 promoted gastric cancer progression through the MFAP5/Notch2/HEY1 signaling axis." (PMID 39524442, 2024). "Conversely, progression of gastric cancer was inhibited by upregulated CTSF promoted by LINC00982 binding to transcription factor HEY1." (PMID 34923982, 2021). "LINC00982 can bind to the transcription factor HEY1 and inhibit its expression, and then promote the expression of CTSF by blocking the binding of HEY1 to the CTSF promoter, thus blocking the progression of gastric cancer." (PMID 35771155, 2022).
glomerulosclerosis (3 papers, 2018 to 2023). A hardening of the kidney glomerulus caused by scarring of the blood vessels. "Notch pathway inhibitors were found to weaken glomerulosclerosis and RIF by decreasing the expression of Jagged1, Notch1, NICD1, HEY1, HES1α-SMA, and fibronectin in uremic rats." (PMID 36793762, 2023).
prostate tumors (3 papers, 2014 to 2016). "This negative feed-back loop may explain why Hif1α mRNA levels were only altered in an early stage (18 wks) of prostate tumor development in TRAMP.eJag1 mutants since at late stages (24 wks) modulation of Hey1 mRNA levels may have caused a repressive effect." (PMID 26213336, 2015). "When assessed by RT-qPCR, Hes1 and Hey1 were found significantly decreased in approximately 70% of the prostate tumors that we examined." (PMID 27384993, 2016). "In prostate tumors, the overexpression of PTOV1 was associated with decreased expression of HEY1 and HES1, and this correlation was significant in metastatic lesions." (PMID 24684754, 2014). "Moreover, we have shown that endothelial Jagged1 regulates prostatic tumor cell proliferation and de-differentiation by activating Notch3 and consequently up-regulating Hey1 in tumor cells." (PMID 26213336, 2015).
acute lymphoblastic T-cell leukemia (2 papers, 2017 to 2020). "Only a few genes, such as HES4, HEY1, MYC, NOTCH3, NRARP, and TFRC, are similarly regulated in mutationally activated NOTCH1-driven cancers, such as T-cell acute lymphoblastic leukemia (T-ALL), mantle cell lymphoma (MCL), and breast cancer." (PMID 33003595, 2020). "Interestingly, expressing supra-physiological levels of Notch1 ICD, as determined by the elevated levels of Hey1 expression, did not generate a phenotype, which is in contrast to other situations of hyperactivated Notch signaling, for example in acute lymphoblastic T-cell leukemia." (PMID 29140246, 2017).
acute myeloid leukemia (2 papers, 2024 to 2026). Acute myeloid leukemia (AML) is a group of neoplasms arising from precursor cells committed to the myeloid cell-line differentiation. "Erythroid acute myeloid leukemia (AML) cell line OCI-M2 expresses a particular oncogenic network: IRF6, in concert with ETV2 and HEY1, aberrantly activates NKL homeobox gene NKX2-4, which in turn represses megakaryocytic lineage factor FLI1." (PMID 41892358, 2026).
adenoid cystic carcinoma (2 papers, 2020 to 2024). A malignant tumor arising from the epithelial cells. "As another pivotal member of the NOTCH1 signaling path, we investigated the expression of HEY1 in salivary adenoid cystic carcinoma, including 77 samples of normal tissue and 87 adenoid cystic carcinoma cases, via immunohistochemistry." (PMID 32025208, 2020). "Immunohistochemistry was used to detect the expression of NOTCH1 and HEY1 in 27 cases of the adenoid cystic carcinoma tissues." (PMID 32025208, 2020). "Furthermore, the expression of NOTCH1 and HEY1 exhibited clearly positive correlation in adenoid cystic carcinoma tissues." (PMID 32025208, 2020). "Interestingly, the Notch-associated bHLH transcription factor HEY1 was also identified as a target DEG and showed the strongest downregulation amongst Notch signaling genes, despite being previously reported as a positively regulated NOTCH1 effector in adenoid cystic carcinoma cells." (PMID 38994994, 2024). "HEY1 expression was absent or low in normal salivary gland tissues, while higher expression levels were observed in the adenoid cystic carcinoma cases (P<0.001)." (PMID 32025208, 2020).
adenoma (2 papers, 2017 to 2020). A neoplasm arising from the epithelium. "Notch target genes, Hes1, Hes5, Hey1, and Hey2, were upregulated ≥2-fold in 33%, 31%, 24%, and 32% of CRCs, respectively, whereas in adenomas, they were overexpressed in 22%, 22%, 11%, and 11%, respectively." (PMID 32211044, 2020). "KrasG12D upregulates expressions of Notch2, Notch3, Notch4, Jag1 and downstream target genes Hes1, Hey1 and Hey2, and deletion of Jag1 partially suppresses KrasG12D-induced adenoma development." (PMID 29142904, 2017).
Ewing sarcoma (2 papers, 2016 to 2023). A small round cell tumor that lacks morphologic, immunohistochemical, and electron microscopic evidence of neuroectodermal differentiation.
hemangioma (2 papers, 2011 to 2023). A benign vascular lesion characterized by the formation of capillary-sized or cavernous vascular channels. "Protein expression evaluation by immunofluorescence confirms that HEY2 is expressed by HemECs (CD31+ cells), while HEY1, HEYL, and HES1 are more widely expressed and mostly expressed by perivascular cells of hemangiomas." (PMID 21834989, 2011).
Infantile hemangioma (2 papers, 2011 to 2023). "Infantile hemangioma endothelial cells (HemECs) express Notch1, Jagged, Hey1, and other molecules in the Notch pathway, suggesting that Notch pathway-related molecules play an important role in affecting vascular endothelial cell proliferation." (PMID 37565874, 2023). "After analysis of eight members of the HES/HEY family, we found that HES1, HEY1, HEY2 and HEYL are expressed in infantile hemangiomas." (PMID 21834989, 2011).
lung adenocarcinoma (2 papers, 2024). A carcinoma that arises from the lung and is characterized by the presence of malignant glandular epithelial cells. "Recent studies have reported high levels of HEY1 expression in cisplatin‐resistant lung adenocarcinoma tissues and A549/DDP cell lines." (PMID 38351531, 2024). "The expression level of HEY1 in lung adenocarcinoma is upregulated." (PMID 39351154, 2024).
metastatic disease (2 papers, 2012 to 2023). "Our data suggest that inhibition of Notch3 signaling, and in particular, the Jag2/Notch3/Hey1 axis may be an effective therapy for HNSCC metastatic disease." (PMID 37202533, 2023). "Furthermore, significantly higher nuclear expression of Notch1, -3 and -4, HES-1, and HEY-1 (all p≤0.001) was noted in locally advanced and metastatic tumours compared to resectable cancers." (PMID 23226563, 2012).
neuroblastoma (2 papers, 2018 to 2020). Neuroblastoma (NB) is the most common solid, extracranial childhood tumor.
Obesity (2 papers, 2015 to 2022). Accumulation of substantial excess body fat. "Overall, Coup-tfII and Hey1 appear to follow a similar expression pattern in adipose tissue, adipocytes and endothelial cells upon induction of diet-induced obesity." (PMID 26719988, 2015). "Interestingly, we found that Coup-tfII and Hey1 follow a similar expression pattern in adipose tissue adipocytes and endothelial cells upon induction of diet-induced obesity." (PMID 26719988, 2015). "However, the requirement and role of the COUP-TFII/Hey1 signaling in adipose tissue development and adipocyte differentiation and its potential as future strategy to treat obesity and its related metabolic diseases need further investigation." (PMID 26719988, 2015).
oligodendroglioma (2 papers, 2018 to 2021). A well-differentiated (WHO grade II), diffusely infiltrating neuroglial tumor, typically located in the cerebral hemispheres. "For example, reduced expression of Notch targets, namely HES1, HEY1, and especially HEY2, was seen in clinically progressed oligodendroglioma, while HES5 expression was most associated with shorter survival on multivariable analysis." (PMID 30417117, 2018).
pancreatic adenocarcinoma (2 papers, 2012 to 2016). "Notch3 and HEY-1 have been shown to be prognostic biomarkers in pancreatic adenocarcinoma." (PMID 26673007, 2016).
asthma (1 paper, 2024). "Two other HEY1 variants, rs4739738 and rs13263709, were associated with “asthma” (p = 6.40E-15 and p = 5.06E-12, respectively)." (PMID 39237910, 2024).
autoimmune disease (1 paper, 2019). A disorder resulting from loss of function or tissue destruction of an organ or multiple organs, arising from humoral or cellular immune responses of the individual to their own tissue constituents. "It has been established that IFN-γ signaling acts downstream of notch signaling in HSC development and that IFN-γ could disrupt the expression of Notch target genes HES1 and HEY1 in patients with autoimmune diseases." (PMID 31311586, 2019).
cervical cancer (1 paper, 2019). A primary or metastatic malignant neoplasm involving the cervix. "HEY1 was also induced by hypoxia in a cervical cancer cell line, HeLa, suggesting that hypoxia-induced HEY1 expression is not limited to HCC but it’s universal in other cancer types." (PMID 31819034, 2019).
clear cell sarcoma (1 paper, 2024). A rare malignant neoplasm with melanocytic differentiation characterized by the presence of polygonal or spindle shaped clear cells. "These two forms of HEY1::NCOA2 fusion might be caused by splicing alterations, as an EWSR1::ATF1 fusion was identified in clear cell sarcoma, although we do not have any data." (PMID 39165647, 2024).
colon adenocarcinoma (1 paper, 2020). "Colon adenocarcinoma patients with a higher mRNA expression of Notch3, Notch4, and Hey1 presented significantly a shorter overall survival compared to those with low expression." (PMID 32211044, 2020).
colorectal adenoma (1 paper, 2020). An adenoma that arises from the colon or rectum. "We investigated mRNA expression of four Notch receptors (Notch1–4), five ligands (Jag1, Jag2, Dll1, Dll3, and Dll4), and four target genes (Hes1, Hes5, Hey1, and Hey2) using highly specific TaqMan gene expression assays in colorectal adenomas and cancers." (PMID 32211044, 2020).
diseases of upper respiratory tract (1 paper, 2024). "The strongest respiratory-related association with HEY1 expression across all tissues with available data was “diagnoses—main ICD10: J39 Other diseases of upper respiratory tract” (p = 2.35E-4) and was identified in the minor salivary gland tissue." (PMID 39237910, 2024).
endothelial dysfunction (1 paper, 2023). In vascular diseases, endothelial dysfunction is a systemic pathological state of the endothelium (the inner lining of blood vessels) and can be broadly defined as an imbalance between vasodilating and vasoconstricting substances produced by (or acting on) the endothelium. "The “anti‐endothelial dysfunction (anti‐ED)” list consists of 31 genes that significantly ameliorate the ED phenotypes, with JUNB, NR4A3, SALL4, CSF2 and HEY1 being the top hits." (PMID 38031960, 2023).
head and neck cancer (1 paper, 2019). A primary or metastatic malignant neoplasm affecting the head and neck. "Interestingly, HEY1 is a downstream mediator of Notch-dependent signals, it has a putative role as oncogene (COSMIC) and its expression was recently associated with an EMT phenotype, increased invasion and cell migration as well as Pt resistance in head and neck cancers." (PMID 31491988, 2019).
heart failure (1 paper, 2023). Inability of the heart to pump blood at an adequate rate to meet tissue metabolic requirements. "It has been shown that mice deficient in the Hey1/L gene develop CHD leading to heart failure soon after birth." (PMID 36831251, 2023).
IgA nephropathy (1 paper, 2023). "Some scholars found that the expressions of Notch1 and Jagged1 were significantly upregulated in the kidney tissues of IgA nephropathy, and Notch1, HEY1, and HES1 were significantly reduced after administration of the Notch1 pathway inhibitor DAPT, thereby alleviating RIF." (PMID 36793762, 2023).
inflammatory breast carcinoma (1 paper, 2020). An advanced, invasive breast adenocarcinoma characterized by the presence of distinct changes in the overlying skin. "For example, Sdc-1 expression in inflammatory breast cancer is correlated with CD44, Notch-1, and Notch-3 expression, and siRNA knockdown of Sdc-1 results in a weaker CSC phenotype and reduced expression of Notch-1-4 and Hey1 in inflammatory breast cancer cells." (PMID 33102470, 2020).
lymph node metastasis (1 paper, 2020). "HEY1 immunoreactivity was positively correlated with lymph node metastasis, recurrence and metastasis." (PMID 32025208, 2020).